ADAMTS12 (ADAM metallopeptidase with thrombospondin type 1 motif 12)
Diseases named in the same sentence as ADAMTS12 in open-access papers (continued):
Sharing a sentence is not in itself a finding about the gene and the disease.
tumor (continued). "Therefore, although the absence of fibulin-2 and ADAMTS-12 is not essential for life, they play an important role in the complexity of processes such as tumor progression and inflammation." (PMID 38396702, 2024). "Therefore, ADAMTS12 might be a tumor promoter and responsible for TME status and tumor energy metabolic conversion." (PMID 34040054, 2021). "However, in our samples, the four genes were expressed in T-MSCs, and more modestly in N-MSCs but not (GREM1 and LOXL2) or weakly so (ITGA11 and ADAMTS12) in the tumor cells (data not shown)." (PMID 29503225, 2018). "However, surprisingly tumor tissues expressed higher levels of ADAMTS12 compared to normal colon tissue." (PMID 24213506, 2012). "In addition, a cohort study which analysed 114 RCC patients samples collected from 1990 to 2005 from the Mayo Clinic Rochester has found that ADAMTS12 together with other ECM components, such as lumican and laminin-2, were upregulated in metastatic tumours compared to primary tumours." (PMID 38948119, 2024). "Additionally, we also found that ADAMTS-12 may elicit pro-tumor effects in the absence of fibulin-2." (PMID 24457941, 2014). "Addition of TGF-β to tumor cell-N-MSC co-culture augmented MX2, BST2 and IL6 (right columns) but not ADAMTS12, LOXL2 GREM1 or CHI3L1 expression in N-MSCs." (PMID 29503225, 2018).
cancer (35 papers, 2010 to 2025). A tumor composed of atypical neoplastic, often pleomorphic cells that invade other tissues. "In the case of LUSC, higher ADAMTS12 promoter methylation was associated with stage 2 cancer than stage 1." (PMID 39940703, 2025). "We found the higher expression level of ADAMTS12 in cancer tissues, which was associated with the worse overall survival rate." (PMID 37642715, 2023). "Using TCGA survival data we found that, among the previously unreported cancer-associated genes, inactivating mutations of ADAMTS12 were associated with poor survival." (PMID 32732999, 2020). "Taken together, both in vivo and in vitro experiments demonstrate that ADAMTS-12 expression associates with the differentiation of the cancer cells and has tumorigenesis and antiangiogenic effects." (PMID 24876675, 2014). "ADAMTS-12 was found to play a protective role in angiogenesis and cancer progression via using ADAMTS-12-deficient-mice models." (PMID 24876675, 2014). "Functionally, ADAMTS12 copy number variation has the potential to be relevant to numerous pathogenic processes including those associated with brain dysfunction, autoimmunity, inflammation, and cancer." (PMID 26543751, 2015). "Taking into account the interaction between fibulin-2 and ADAMTS-12, we generated fibulin-2/ADAMTS-12-double-deficient mice and demonstrated that they represent a new and valuable in vivo model for the functional analysis of the interaction of these two proteins in inflammation and cancer processes." (PMID 38396702, 2024). "In this sense, ADAMTS-12 function may depend on several factors, type of cells in which it is expressed (cancer cells, inmune or stromal cells), the appearance of ADAMTS-12 mutants (point mutations, truncated forms, protein processing) as well as the interactions with other components of the ECM." (PMID 33996918, 2021). "While ADAMTS12 is known to contribute to cancer progression and treatment resistance, its prognostic significance and underlying mechanisms in BCa remain poorly understood." (PMID 39761856, 2025). "In contrast, an additional RT-qPCR analysis showed significantly higher levels of ADAMTS12 expression in cancer samples used for the methylation study than in normal tissues." (PMID 39940703, 2025). "In particular, ADAMTS12 enhances cancer cell migration, contributing to the aggressive nature of lung tumors." (PMID 40584122, 2025). "The bioinformatic analyses found the presence of a distinct DMR pattern among ADAMTS6, ADAMTS9, and ADAMTS12 to be a useful tool for distinguishing normal cells from cancer cells." (PMID 39940703, 2025). "Different transcript levels of ADAMTS6, ADAMTS9, and ADAMTS12 are observed in various types of cancer, which points to the problematic part played by these proteases in the pathogenesis of proliferative diseases." (PMID 39940703, 2025). "The differential methylation region (DMR) pattern demonstrated by ADAMTS6, ADAMTS9, and ADAMTS12 is a useful tool for distinguishing normal from cancer cells." (PMID 39940703, 2025). "ADAMTS12 levels were significantly raised in various types of cancer in contrast to the control tissues." (PMID 39761856, 2025). "The ADAMTS12 gene was also upregulated in various cancer types, such as CHOL, COAD, ESCA, HNSC, READ, and STAD." (PMID 39940703, 2025). "Bioinformatic analysis revealed a decrease in the expression of the ADAMTS9 gene and an increase in ADAMTS12 expression in the cancer tissue of patients with NSCLC compared to normal tissue." (PMID 38339175, 2024). "It would be interesting to determine how cancer cells affect protease stromal expression, as well as the molecular mechanisms through which ADAMTS12 opposes cell growth." (PMID 38948119, 2024). "To verify the cancer-promoting phenotype of ADAMTS12 in experiments, we selected HeLa and CaSki to conduct cell functional experiments." (PMID 37642715, 2023). "To explore the cancer-promoting mechanism of ADAMTS12, we first began to search through the bioinformatics level." (PMID 37642715, 2023).
cancer (continued). "We further performed UniCox and Kaplan-Meier analyses to evaluate the prognostic significance of ADAMTS12 in pan-cancer." (PMID 35280819, 2022). "We also performed the correlation analysis between ADAMTS12 and the m6A related genes in pan-cancer." (PMID 35280819, 2022). "The Cancer Genome Atlas (TCGA) and Genotype-Tissue Expression data (GTEx) databases were used to analyze ADAMTS12 expression in pan-cancer." (PMID 35280819, 2022). "With the previous data on mind, analysis and correlation studies are of key importance to decipher the precise role of ADAMTS-12 in cancer development." (PMID 33996918, 2021). "Gene Set Enrichment Analysis (GSEA) indicated that in high ADAMTS12 expression group gene sets were mainly enriched in cancer and immune-related activities." (PMID 34040054, 2021). "Consistent with mRNA data, ADAMTS12 protein levels in cancer tissues were also significantly increased, with a mean value of 5.5 compared with normal tissues as 1.0." (PMID 34040054, 2021). "It is noteworthy that ADAMTS12, AMACR, SLC45A2 and C1QTNF3 are associated with cancers, which are all hallmarked by CIN (aneuploidy)." (PMID 26543751, 2015). "The gene expression data available in the databases indicated differences between tumors and normal tissue with regard to the regulation of ADAMTS6, ADAMTS9, and ADAMTS12, which may be related to their different roles in cancer pathogenesis." (PMID 39940703, 2025). "ADAMTS12 plays an oncogenic role in the progression of multiple human cancers." (PMID 38167385, 2024). "Several studies have investigated the role of ADAMTS12 in the context of cancer development." (PMID 39286973, 2024). "Thus, we inferred that PREX2, ADAMTS12, and PLXDC2 mutations lead to cancer development at both the protein function and posttranscriptional regulation levels." (PMID 35654793, 2022). "In this study, the role of ADAMTS12 in pan-cancer was comprehensively analyzed using data from the TCGA database, which includes data on expression, clinical features, prognostic significance, copy number alteration (CNA), DNA methylation level, and genomic mutation." (PMID 35280819, 2022). "Notably, some identified 3′-UTR piSNV-affected genes, such as PREX2, ADAMTS12, and PLXDC2, were regarded as cancer-related genes with a high deleterious mutation rate." (PMID 35654793, 2022). "Our study implicates the targeting of ADAMTS12 as a potential method of anti-cancer therapy." (PMID 35280819, 2022). "The biological function of ADAMTS12 in malignant tumors is still ambiguous." (PMID 34040054, 2021). "In addition, ADAMTS-12 participation in the resolution of inflammatory processes should also be taking into account in local cancer development." (PMID 33996918, 2021). "Moreover, the ADAMTS-12 expression in cancer stroma of patients with lymph node metastasis was greater than that within the patients without lymphatic metastasis." (PMID 24876675, 2014). "However, subsequent reports by several groups on ADAMTS12 in cancers suggest otherwise." (PMID 24213506, 2012). "In esophageal squamous cell carcinoma, ADAMTS12 is one of the downstream regulatory targets of lncRNA HCG22, which plays a role in suppressing cancer progression." (PMID 37642715, 2023). "For example, MAPK8IP2, ADAMTS12, and CHAF1B were upregulated in over five cancer types, while HHIP, PROX1, and PLCG2 were downregulated in over five cancer types." (PMID 35654793, 2022). "However, the role of ADAMTS12 in pan-cancer and especially in PAAD remains unclear." (PMID 35280819, 2022). "Members of the ADAMTS family, such as ADAMTS2, ADAMTS5, ADAMTS12, and ADAMTS15, can act as cancer suppressors or promoters." (PMID 33921267, 2021). "LRFN4, ADAMTS12, MCEMP1, HP and MUC15 are all cancer-related biomarkers, and all of them can also be used in judgment of cancer incidence in an independent manner." (PMID 32908454, 2020).
cancer (continued). "In summary, ADAMTS12 is a tumor suppressor gene, inhibiting tumorigenesis by directly blocking Ras-dependent ERK pathway in cancer cells as well as indirectly by suppressing angiogenesis through its TSR containing ancillary domains." (PMID 24213506, 2012). "Absence of ADAMTS-12 in mice, although proven to be involved in cancer and inflammatory processes, has not shown an effect in normal development." (PMID 38396702, 2024). "Members such as ADAMTS2, ADAMTS5, ADAMTS12, and ADAMTS15 act as cancer suppressors or promoters." (PMID 33921267, 2021). "Interestingly, ADAMTS12 has been shown to have both pro- and anti-tumorigenic activities, while very little is still known about the role of ADAMTS2 in cancer." (PMID 27128408, 2016). "They play a dual role in cancer; for instance, ADAMTS14 works as a promoter of hypermethylation and acts as a tumor suppressor gene, whereas others show upregulation in cancer acting as oncogenes, including ADAMTS12, which regulated the cell proliferation and migration in colorectal cancer." (PMID 35743687, 2022). "For example, ABCA5, ADAMTS12 and CLEC3B have not been reported to be cancer related." (PMID 21060876, 2010).
neurological disorders (2 papers, 2021 to 2022). "Two of the lead genetic variants (rs111836296 and rs74710969) were extremely rare in Europeans and lie in or tag candidate genes (IL15 and ADAMTS12) linked to AD and other neurological disorders." (PMID 35396452, 2022).
ADAMTS12 also shares sentences with these, for which no sentence is quoted: infection (2 papers); pancreatitis (2); prostate carcinoma (2); rheumatoid arthritis (2); Sepsis (2); acute kidney injury (1); adenocarcinoma (1); bipolar disorder (1); brachydactyly type E (1); brain disorder (1); cardiomyopathies (1); cardiovascular diseases (1); cerebral aneurysms (1); chronic kidney disease (1); congenital malformations (1); cutaneous melanoma (1); deafness (1); developmental delay (1); esophageal cancer (1); GI tumors (1); head and neck squamous cell carcinoma (1); intervertebral disc degenerative disease (1); kidney injury (1); mastitis (1); narcolepsy (1); non-melanoma skin carcinoma (1); oculocutaneous albinism (1); pancreatic ductal adenocarcinoma (1); Parkinson’s (1); Pigmentary retinopathy (1).
A further 3 diseases each share a sentence with ADAMTS12 in 1 paper.